CXCL8 (C-X-C motif chemokine ligand 8)
Diseases named in the same sentence as CXCL8 in open-access papers (continued):
Sharing a sentence is not in itself a finding about the gene and the disease.
tumor (continued). "Given that the downstream intracellular targets of CXCL8 include STAT3, increased CXCL8 in the tumour stroma promotes a positive intercellular feedback loop between CXCL8 and IGF-2 production." (PMID 26465273, 2015). "The tumor secretes chemokines CXCL8, CCL2, IL-1, and TNF-α that recruits macrophages and suppressive CD4+CD25+CD127lowFOXP3+ Tregs to the tumor site." (PMID 25972872, 2015). "The resultant stromal production of several cytokines, especially CXCL8, provides proangiogenic signals and increases metastatic potential in tumours." (PMID 26465273, 2015). "Recent study on hepatocellular carcinoma indicated importance of CXCL16 and its receptor CXCR6 in neutrophil recruitment and tumor progression, due to its ability to stimulate tumor cells to release CXCL8." (PMID 26648665, 2015). "We suggest that expression of HIF-1α and serum levels of CXCL8 are predictive markers of tumor recurrence and prognosis." (PMID 26078356, 2015). "Expression of HIF-1α and CXCL8 was higher in HCC tissues compared to adjacent non-tumor liver tissues." (PMID 26078356, 2015). "During the refractory phase, tumor-secreted CXCL8 (IL-8) levels increased > 4 folds (P < 0.05) in the sorafenib-resistant tumors." (PMID 26414070, 2015). "Hypoxia inducible factor-1α (HIF-1α), induces cytokines such as CXCL8 and tumor dissemination, chemo- and radio-resistance." (PMID 26078356, 2015). "In conclusion, we showed that increased expression of HIF-1α and CXCL8 in HCC correlate with tumor progression, metastasis and, a poor survival." (PMID 26078356, 2015). "After we first observed a higher HIF-1α and CXCL8 expression in 102 HCC samples (as compared to matched adjacent non-tumor liver tissues), we additionally found a correlation between the expression level and tumor features." (PMID 26078356, 2015). "In pancreatic cancer, tumor cells secrete CXCL8 and CAFs secrete CXCL12 to enhance the recruitment and proliferation of ECs." (PMID 25110692, 2014). "In this study, when CXCL8 was depleted, there was a significant reduction in tumor size, tumor induced angiogenesis, and metastases." (PMID 24971349, 2014). "In parallel, we found that wild-type Ras (WT-Ras) has cooperated with TNFα, and these two elements together gave rise to the amplified expression and release of CXCL8 by the tumor cells." (PMID 24598028, 2014). "The results obtained thus far in this study indicate that the cooperative activities of TNFα with RasG12V or with WT-Ras lead to additive elevation in the release of CXCL8 by the tumor cells." (PMID 24598028, 2014). "Tumor-bearing animals depleted of CXCL-8 demonstrated a 40% reduction in tumor growth and in spontaneous metastasization that directly correlated to reduced angiogenesis." (PMID 24971349, 2014). "It is possible that the release of EGF and many other RTK ligands (e.g., VEGF, bFGF, HGF) is induced as a consequence of TNFα activation, leading to RTK activation and then to cooperation in the release of CXCL8 by the tumor cells." (PMID 24598028, 2014). "CXCL8 (interleukin-8) was involved in tumor cell proliferation via the transactivation of the epidermal growth factor receptor (EGFR)." (PMID 24629040, 2014). "ELR+ CXC chemokines, such as CXCL-8, have been determined to play a critical role in tumor growth and metastases." (PMID 24971349, 2014). "Higher expressions of CXCR1, CXCR2, and CXCR4 with their ligands CXCL5, CXCL8, and CXCL12 appear to be associated with tumor angiogenesis, metastasis, and poor survival in NSCLCs." (PMID 25271023, 2014). "Noteworthy, Haim and coworkers reported that estrogen upregulates the transcription and secretion of CXCL8 in breast tumor cells additively through estrogen receptor α (ERα), adding a novel role of estrogen in promoting tumor growth." (PMID 25165728, 2014). "Accordingly, the expression of CXCL8 correlated with tumor vascularization, aggressiveness, invasion, and metastasis and with poor prognosis in patients with gastric adenocarcinoma." (PMID 24971349, 2014).
tumor (continued). "The results indicate that CM derived from TNFα-stimulated WT-Ras-expressing tumor cells (shown to produce highly elevated levels of CXCL8) induced significantly stronger angiogenic effects compared to control cells." (PMID 24598028, 2014). "This cluster included the highly angiogenic, malignancy-promoting chemokine CXCL8, as well as the tumor-promoting chemokine CCL2." (PMID 24598028, 2014). "For either of these phenotypes, we observed that the efficacy of the stromal-derived chemokine required the presence of tumor-derived CXCL8 signaling." (PMID 24970800, 2014). "CXCR1/2 expressed by vascular ECs and CXCL8, the ligand produced by tumor and stromal cells, are known to promote angiogenesis through inducing EC migration and formation of tubules." (PMID 25110692, 2014). "The direct relationship between tumor-derived CXCL-8 and tumorigenesis was demonstrated in in vivo model of human tumorigenesis (i.e., human NSCLC/SCID mouse chimera)." (PMID 24971349, 2014). "In that manner, the two components together induce the up-regulation of CXCL8 (and possibly of other tumor-promoting and angiogenic factors) and angiogenesis." (PMID 24598028, 2014). "In vitro studies demonstrated functional co-operation of tumor-derived CXCL8 with stromal-derived chemokines." (PMID 24970800, 2014). "Depletion of endogenous CXCL8 inhibited PC-3 tumor growth in SCID mice that was entirely attributable to inhibition of tumor-derived angiogenesis." (PMID 24971349, 2014). "Instead, integrating our observations in tumor and stromal cell lines, we propose that tumor-derived CXCL8 signaling initiates a co-ordinated chemokine-driven cross-talk between tumor and stromal cells." (PMID 24970800, 2014). "We observed that blockade of endothelial cell-derived IL-6 inhibited STAT3 phosphorylation in cancer cells and expression of CXCL8 (IL-8), a potent pro-angiogenic factor that is strongly correlated with tumor microvessel density." (PMID 24533454, 2014). "TNFα, a cytokine released into the TUMIC and linked to tumor progression, induces neutrophil degranulation and VEGF release and CXCL8, CXCL1 production, thus favoring angiogenesis." (PMID 25072019, 2014). "Anti-CXCL8 antibodies would also fail to inhibit any tumor-promoting MIF signaling, which has previously been demonstrated to potentiate growth of PC3 tumors in vivo." (PMID 24276377, 2013). "Multiple studies have used CXCL8 neutralizing antibodies to reduce tumor burden in mouse models, the results of which have been mainly attributed to the inhibition of CXCL8’s angiogenic properties." (PMID 24276377, 2013). "Both soluble and cellular factors are involved in tumor and stroma interactions, including CXCL8, TGFβ, and metalloproteases." (PMID 23951028, 2013). "Studies in two androgen-independent models, PC3 and DU145 cells, confirmed that CXCL8 signaling can up-regulate cyclin D1 expression promoting tumor cell proliferation." (PMID 24276377, 2013). "The chemokine CXCL8, also known as interleukin-8 (IL8), is a proinflammatory molecule that has functions within the tumor microenvironment." (PMID 24224100, 2013). "Despite the dominant effect of CXCL8, the dynamics of chemokine release and activity in the tumor microenvironment are complex, and the balance between CXCL8 and other cytokines should be considered." (PMID 24224100, 2013). "In the case for PDAC, several factors have been shown to be involved in tumor and stroma interactions including CXCL8, TGF-β and metalloproteases, all observed in our PDAC-CAF cross talk system." (PMID 23951028, 2013). "This review relates the current understanding of the regulation, signaling, and functions of CXCL8 that contribute to tumor growth and metastasis, and of its role in drug response." (PMID 24224100, 2013). "The CXCL8 expressed in tumor cells is also secreted by OSCC cell lines, and CXCL8 mRNA expression is enhanced by the addition of TNF-α and IL- 1β." (PMID 23365550, 2013).
tumor (continued). "Immunohistochemical analysis of the primary tumor sections was done using an anti-CXCL-8 mouse monoclonal antibody to evaluate the expression of CXCL-8." (PMID 23342280, 2012). "In contrast, a significant decrease in tumor growth (2.0-fold) was observed in the A375SM-anti-CXCL-8 group as compared with the A375SM-control group." (PMID 23342280, 2012). "Having confirmed the effect of CXCL-8 on tumor growth, we next examined its role in neovascularization in vivo." (PMID 23342280, 2012). "Chemokines such as CXCL1 and CXCL8 are able to enhance tumor cell proliferation; CXCL5 and CXCL12 attract neutrophils and MDSC, while CXCL12 promotes the migration of tumor cells that express the cognate receptor CXCR4." (PMID 22927846, 2012). "We observed that the CXCL-8 level is a direct indicator of multiple tumor behaviors, including growth, angiogenesis, and metastasis." (PMID 23342280, 2012). "Our data demonstrate that overexpression of CXCL-8 significantly enhanced primary tumor growth and lung metastasis, accompanied by increased microvessel density in vivo, as compared with vector control-transfected cells." (PMID 23342280, 2012). "Tumor hypoxia upregulated CXCL-8 production is also credited for increased tumor dissemination and aggressiveness." (PMID 23342280, 2012). "The chemokines CXCL1, -2, -3, -5, and IL8 (CXCL8) were among the top-210 genes that were observed to be upregulated in metastases compared with primary tumours, and they showed highly correlated expression patterns." (PMID 22518090, 2012). "In contrast, in A375SM-anti-CXCL-8 tumors, we observed a 3.3-fold decrease in the number of tumor blood vessels as compared with A375SM-control tumors." (PMID 23342280, 2012). "A375P- and A375SM-derived heterogeneous populations were used to study the effect of CXCL-8 on tumor cell growth in immunodeficient mice." (PMID 23342280, 2012). "Knockdown of CXCL-8 using an antisense vector resulted in increased cell death and reduced tumor growth relative to control." (PMID 23342280, 2012). "On the one hand, CXCL-8 can be stimulated by a stress environment or pre-inflammatory cytokines to rescue cell death or promote tumor progression." (PMID 23342280, 2012). "To understand the role of CXCL-8 in tumor progression, we used transwell assays to analyze migration through a porous membrane toward serum (chemotaxis) for cells with different levels of CXCL-8." (PMID 23342280, 2012). "In our in vivo studies, a significant increase in blood vessel number and density was found in A375P- and A375SM-derived tumor sections with higher CXCL-8 levels, as compared with their counterparts." (PMID 23342280, 2012). "Different inflammatory mediators, for example, cyclooxygenase-2 (COX-2), IL-1, IL-6, TGFβ and CXCL8, and their receptors are present in the tumor milieu." (PMID 22190968, 2011). "Increased secretion of CXCL1 and CXCL8 from tumour epithelium has also been reported to induce angiogenesis in gastro-intestinal cancers." (PMID 21285972, 2011). "For example, tumour infiltrating inflammatory cells elevates CXCL8 levels in bronchioalveolar cells, along with its two receptors." (PMID 21298036, 2011). "A recent study found that tumour derived CXCL8 acted as an attractant for circulating tumour cells to return to the original tumour, leading to a more aggressive tumour phenotype." (PMID 21298036, 2011). "Multivariate analysis using Cox regression proportional hazard analysis confirmed disease stage and tumour infiltrate CXCL8 expression as independent predictors of RFS across the study cohort." (PMID 21285972, 2011). "Our study addressed this question in relation to CXCL8 expression, and provides novel clinical evidence linking such expression specifically within the tumour infiltrate and within these well-defined disease stages to improved patient outcome." (PMID 21285972, 2011).
tumor (continued). "The good prognostic effect conferred by the infiltrate's CXCL8 positivity most likely reflects the immune functions of this chemokine and the anti-tumour role of the inflammatory cells." (PMID 21285972, 2011). "The CXCL8 positivity in the tumour infiltrate, however, correlated with earlier disease stage (P<0.001) and improved relapse-free survival across the cohort (P<0.001)." (PMID 21285972, 2011). "Intrahepatic lymphocytes, isolated from non-tumor tissue, were stimulated with peptides overnight and culture supernatants were screened for CXCL-8, CXCL-9, CXCL-10, CCL-5, CCL-2 as well as IL-17 and the anti-inflammatory cytokine IL-10." (PMID 21876747, 2011). "Univariate analysis of the entire cohort showed that disease stage (P<0.001), and interestingly, expression of CXCL8 within the tumour inflammatory infiltrate (P<0.001) was the only significant factors impacting on recurrence-free survival (RFS)." (PMID 21285972, 2011). "Of note, when the main producers of the inflammation, i.e. tumor cells and fibrotic stroma, were removed the systemic levels of CXCL8 and PGE2 in blood were decreased." (PMID 20976171, 2010). "We investigated the effect of CXCL8 on cellular proliferation since humanised CXCL8 antibody has recently been shown to inhibit tumour growth in vivo." (PMID 19819266, 2009). "Tumour-associated macrophages are known to contain many proangiogenic factors, such as VEGF, TNF-α, CXCL-8, bFGF and proteases such as MMP-2 and MMP-9." (PMID 19352388, 2009). "As RCAN1-4 expression reduces over time, the expression of CXCL8 increases to promote tumour cell proliferation." (PMID 19819266, 2009). "Others work by modifying the extracellular environment of the tumor, including bFGF, Interleukin-8 (IL-8/CXCL8), and Platelet-derived Growth Factors-AA and -AA/BB (PDGFs)." (PMID 18616824, 2008). "For CXCL8 we also observed on the protein level that the expression was significantly higher in tumor stage 4 in comparison to the lower tumor stages." (PMID 18578857, 2008). "Mechanistically, this subset responds to hypoxia by expressing VEGFA to directly promote tumor angiogenesis while highly expressing the chemokines CXCL2, CXCL3, and CXCL8 to establish a chronic inflammatory microenvironment that indirectly fosters tumor progression and vascularization." (PMID 41514936, 2026). "The potential of CXCL8 as a therapeutic target is underscored by the fact that an anti‐CXCL8 monoclonal antibody can enhance antitumour immunity in triple‐negative breast cancer and inhibit the recruitment of neutrophils into the tumour." (PMID 41503514, 2026). "Notably, several soluble factors associated with NET induction, including CXCL2, CXCL8, and IL‐6, were markedly upregulated in PUS7‐overexpressing tumour cells compared with controls." (PMID 41496500, 2026). "Their polarization is shaped by ELR+ CXC chemokines (CXCL1, CXCL8), cytokine signals, systemic inflammation, hypoxia driven by VHL/HIF pathways, and tumor-intrinsic oncogenic alterations such as PTEN loss, ERβ- and c-Myc-dependent programs, as well as epigenetic remodeling." (PMID 41705247, 2026). "Given that CCL2, GM-CSF, and CXCL8 primarily function within the tumor microenvironment, we expected that other N4BP1 targets might directly affect cancer cells." (PMID 41513619, 2026). "Moreover, tumour cells, as well as cancer‐associated endothelial cells and fibroblasts, express chemokines such as CXCL1, CXCL2, CXCL5, CXCL6 and CXCL8 (IL‐8)." (PMID 41503514, 2026). "NE are actively recruited to the GBM microenvironment through chemotactic signals such as C-X-C motif chemokine ligands 1, 2 and 8 (CXCL1, CXCL2, and CXCL8) secreted by tumor cells, stromal cells, and infiltrating immune cells, allowing selective NE accumulation at the tumor site." (PMID 40006088, 2025).
tumor (continued). "Moreover, Non-Responders exhibited upregulation of chemokines including CXCL1 and CXCL8 and enrichment of immunoregulatory M2 macrophages in tumor regions, suggesting active macrophage recruitment from the stroma." (PMID 41388608, 2025). "Taken together, our study points toward the possibility that Fusobacterium may promote tumor growth by inducing CXCL8 production in human CRC cancer cells." (PMID 40895532, 2025). "Furthermore, HGGs are known to be resistant to immune checkpoint blockade therapy, partly due to a subpopulation of CD4 + T cells that express CXCL8 and contribute to tumor growth and reduced efficacy of immune checkpoint inhibitors." (PMID 41432874, 2025). "CXCL8 has a significant impact on disease prognosis and tumor immunity in Gr." (PMID 41432874, 2025). "CXCL6 and CXCL8 play significant roles in tumor progression and inflammatory responses." (PMID 40696350, 2025). "By regulating the migration and function of immune cells in the TME, CXCL8 may support immune escape of tumor cells." (PMID 41376630, 2025). "Furthermore, Maelstrom (MAEL) increases phosphorylated Akt1 expression in tumor cells, which phosphorylates the NF-κB subunit RelA, resulting in MDSC chemotaxis through the upregulation of CXCL8, thereby accelerating tumor progression within the TME." (PMID 40134607, 2025). "In addition, we found that CAF_C3 highly expressed CXCL3 and CXCL8, which are known to play critical roles in tumor progression." (PMID 40725006, 2025). "By disrupting neutrophil recruitment, therapies targeting CXCR2/CXCL8 may enhance the immune response against the tumor and improve the efficacy of other cancer treatments, including immunotherapies." (PMID 40486614, 2025). "Our data suggest that CXCL8 may contribute more prominently to tumor progression or immune evasion mechanisms during recurrence, possibly via modulation of macrophage polarization or cytokine signaling pathways." (PMID 41432874, 2025). "Furthermore, CXCR2+ immune cells were more abundant in stroma-rich primary and metastatic tumor tissues, suggesting a role for the CXCL8/CXCR2 axis in promoting an unfavorable tumor phenotype and supporting immunosuppression." (PMID 40943634, 2025). "Blocking this CXCL8/CXCR2/GAG axis is a novel therapeutic strategy that could potentially reverse the tumor immune evasion." (PMID 40124384, 2025). "RT-qPCR confirmed that MMP1, TFRC, and CXCL8 were upregulated in tumor tissues." (PMID 40809844, 2025). "Moreover, TAMs facilitate the recruitment/activation of ECs via a variety of secreted factors, such as VEGFA and CXCL8, to ensure an “economic benefit” for tumor growth by supplying tumor cells with nutrition." (PMID 41346571, 2025). "Additionally, the canonical NF-κB pathway also promotes angiogenesis by regulating pro-angiogenic genes such as vascular endothelial growth factor (VEGF) and CXC chemokine ligand 8 (CXCL8), facilitating tumor invasion." (PMID 40760228, 2025). "In addition, CXCL8 (IL‐8) acts as a powerful signaling agent that attracts endothelial cells to the tumor and stimulates them to form new blood vessels." (PMID 40145607, 2025). "However, in the context of cancer, CXCL8 is produced by various cell types within the tumor microenvironment (TME), including infiltrating immune cells, stromal cells, and tumor cells." (PMID 40573881, 2025). "Furthermore, their findings confirmed that the surgical resection of the tumor resulted in an immediate decrease in serum CXCL8 levels, highlighting its potential as a biomarker for tumor burden." (PMID 40649964, 2025). "Furthermore, elevated expression of CXCL8 and CXCR2 is linked to tumor progression, metastasis, and unfavorable prognosis in patients with ESCC." (PMID 40134607, 2025).